COA8 (cytochrome c oxidase assembly factor 8)
Description:
Required for cytochrome c complex (COX) IV assembly and function Protects COX assembly from oxidation-induced degradation, COX being the terminal component of the mitochondrial respiratory chain.
Synonyms: APOP-1; APOP1; APOPT1; C14orf153; MGC2562; APOP; MC4DN17
Tractability: Antibody: UniProt places it where antibodies can reach, with high confidence. PROTAC: UniProt records ubiquitination sites on it.
Gene: Protein-coding gene on chromosome 14 (103,562,960 to 103,607,523, forward strand). Ensembl gene ENSG00000256053.
Subcellular location: Mitochondrion inner membrane
Gene Ontology:
Molecular function: protein binding
Biological process: mitochondrial respiratory chain complex IV assembly; protein stabilization; response to reactive oxygen species; intrinsic apoptotic signaling pathway
Cellular component: matrix side of mitochondrial inner membrane; mitochondrial inner membrane; mitochondrion
Genetic constraint (gnomAD): Loss-of-function variants: 19 observed, 21.35 expected, observed/expected ratio (o/e) 0.89, 90% interval 0.62 to 1.3. The synonymous counts are far from expectation, so gnomAD's model fits this gene poorly and the ratio says little. Missense variants: 258 observed, 214.89 expected, observed/expected ratio (o/e) 1.2, 90% interval 1.08 to 1.33. Synonymous variants: 105 observed, 75.46 expected, observed/expected ratio (o/e) 1.39, 90% interval 1.19 to 1.64.
Gene-disease validity (ClinGen):
ClinGen rates the evidence that COA8 causes each of these diseases.
mitochondrial disease (autosomal recessive): Definitive.
Homologues: Orthologues: chimpanzee COA8 (99% identical), dog COA8 (83% identical), mouse Coa8 (75% identical), pig COA8 (75% identical), guinea pig COA8 (72% identical), rat Coa8 (50% identical), zebrafish coa8 (45% identical), Drosophila melanogaster Coa8 (32% identical), Caenorhabditis elegans Y39B6A.34 (23% identical).
Diseases named in the same sentence as COA8 in open-access papers:
COA8 is named in the same sentence as 15 diseases in open-access papers, as found by Europe PMC text mining. Sharing a sentence is not in itself a finding about the gene and the disease. The quoted sentences say what the papers report.
Leukoencephalopathy (7 papers, 2014 to 2024). This term describes abnormality of the white matter of the cerebrum resulting from damage to the myelin sheaths of nerve cells. "Loss-of-function COA8 mutations have been associated with cavitating leukoencephalopathy with COX deficiency in 9 reported individuals." (PMID 38098475, 2023). "The long-term outcome of the disease seems in general to be favorable, and the characteristic MRI pattern with cavitating leukoencephalopathy in combination with COX deficiency should prompt for testing of the APOPT1/COA8 gene." (PMID 32637636, 2020). "Our study provides additional evidence for an association between COA8 and leukoencephalopathy with complex IV deficiency, typical MRI pattern, and characteristic clinical course." (PMID 32637636, 2020). "Biallelic APOPT1/COA8 variants have been shown to cause COX deficiency and cavitating leukoencephalopathy." (PMID 33426505, 2020). "While we note that mutations have also been identified in cases of leukoencephalopathy in both COA7 and COA8/APOPT1, neither of these human COX assembly factors appear to have yeast homologues and were therefore not discussed in any depth." (PMID 38612624, 2024).
leukodystrophy (3 papers, 2014 to 2023). Leukodystrophies are a group of rare, progressive, metabolic, genetic diseases that affect the brain, spinal cord and often the peripheral nerves. "Patients deficient in COA8 show specific COX deficiency with distinctive neuroimaging features, i.e., cavitating leukodystrophy." (PMID 31555154, 2019).
Mitochondrial encephalopathy (1 paper, 2019). "For instance, loss-of-function mutations in the COA8 gene (alias APOPT1, APOP-1, or C14ORF153) have been identified in seven subjects from six different families presenting a distinctive form of mitochondrial encephalopathy." (PMID 31555154, 2019).
Mitochondrial myopathy (1 paper, 2023). "We describe an Italian familial case of mitochondrial myopathy due to a variant in the COX assembly factor 8 gene (COA8)." (PMID 38098475, 2023). "By identifying a likely causative novel pathogenic variant in a familial case of mitochondrial myopathy, this study expands the clinical and molecular features of COA8-related disorders." (PMID 38098475, 2023). "Our findings reinforce this concept also for COA8 and prompt the consideration of this gene even in patients presenting primary mitochondrial myopathy as the preeminent clinical manifestation." (PMID 38098475, 2023).
COA8 also shares sentences with these, for which no sentence is quoted: cancer (3 papers); mitochondrial disease (3); schizophrenia (3); tumor (2); Alzheimer disease (1); brain disorder (1); Encephalopathy (1); nasopharyngeal carcinoma (1); osteosarcoma (1); psychiatric disorder (1); squamous cell carcinoma (1).